EGFR (epidermal growth factor receptor)
Diseases named in the same sentence as EGFR in open-access papers (continued):
Sharing a sentence is not in itself a finding about the gene and the disease.
cancer (continued). "AKT1, EGFR, SRC, ESR1, and PTGS2 are the top five targets in the PPI network, and they were reported as critical regulatory factors in cancer metastasis and EMT." (PMID 35942366, 2022). "Given the dramatic activity of these cancers and the overexpression of EGF biomarkers in up to 66% of TNBCs, efforts to target EGFR in BC have focused on TNBC." (PMID 36358874, 2022). "There are currently several targeted cancer therapies, such as BRAF inhibitors, MEK inhibitors and epidermal growth factor receptor (EGFR) tyrosine kinase inhibitors." (PMID 36347846, 2022). "Thus, EGFR-targeting peptides may be a better candidate for a new cancer imaging agent." (PMID 35120180, 2022). "Recent studies have demonstrated that NF-κB and EGFR are partners in cancer, and NF-κB-induced KIAA1199 promotes EGFR stability, contributing to the activation of the NF-κB/EGFR signaling pathway." (PMID 36291177, 2022). "The epidermal growth factor receptor (EGFR) is a key player in the normal tissue physiology and the pathology of cancer." (PMID 36185288, 2022). "The activation of this signaling cascade was correlated with enhanced OSCC cancer stemness and elevated expression of CD44 and epidermal growth factor receptor (EGFR)." (PMID 35706019, 2022). "In vitro experiments suggest that overexpression of EGFR inhibits Bim through the MAPK pathway and thus induces anoikis resistance in malignant tumors." (PMID 36046036, 2022). "Upon epidermal growth factor (EGF) binds to EGFR, it activates AKT-mediated cancer cell proliferation and metastasis." (PMID 35572726, 2022). "Monoclonal antibodies targeting the epidermal growth factor receptor (EGFR), including cetuximab and panitumumab, have been used in clinic settings to treat cancer." (PMID 35798841, 2022). "The upregulation of ZBTB10 and ZBTB4 expression inhibited SP transcription factors and, as a result, the expression of several downstream target genes such as EGFR, c-MET, cyclin D1, and NFB, resulting in cancer cell growth inhibition and apoptosis induction." (PMID 35530318, 2022). "As approximately 10% of studied cancer cells survive even under high concentrations (up to 5 U/mL) of MGL S3, we decided to test its ability to work with the known EGFR inhibitor gefitinib." (PMID 36361596, 2022). "Here we detected that A549 cancer cells cultured with higher extracellular glucose concentrations have upregulated IGF1R and EGFR expression on their cell membrane." (PMID 35574343, 2022). "The expression of EGFR and Notch1, a member of the NOTCH family of transmembrane proteins that regulate many basic processes essential for cancer development and progression, was significantly associated with poor survival outcomes in TBSCC." (PMID 35562926, 2022). "Activation of interleukin-6 (IL6) and epidermal growth factor receptor (EGFR) pathways, and key genes in cancer-related glucose metabolic reprogramming, were validated in TAA-CCAs." (PMID 35619118, 2022). "The results obtained demonstrated that the mAb-EGFR complex was markedly and synchronously internalized via the p38-mediated phosphorylation of EGFR upon a stimulation with TNF-α and cytotoxic anti-cancer agents." (PMID 35798841, 2022). "The binding of transforming growth factor-β to its receptor TβR can activate the EGFR, angiogenesis, and the epithelial–mesenchymal transition (EMT) in cancer cells." (PMID 36547898, 2022). "Increased levels of activation upstream of receptor tyrosine kinase TRKB, EGFR, and MAPK signaling were seen in copper-treated cancer cells." (PMID 36553481, 2022). "The increased Hsp90 expression along with its client proteins, EGFR, IGF-1R, and Src, promotes autophagy in cancer cells and confers drug resistance." (PMID 36348391, 2022).
cancer (continued). "There were no significant changes in gene expression levels for the seven other cancer genes (ABCC1, ALK1, BRCA1, DHRS2/HEP27, EGFR, ERBB2, and ERCC1)." (PMID 35743133, 2022). "A large ECM CSPG (Versican) was observed to promote cancer epithelial-to-mesenchymal transition (EMT) and metastasis through EGFR/AKT, Snail/PAPSS2 and TGFβ/NK-κB signaling in liver, breast and ovarian cancers." (PMID 36612261, 2022). "Specific Glycine-to-Leucine mutations in the TMD disrupt oligomerization and inhibit the Epidermal Growth Factor Receptor (EGFR) and EGFR-driven cancer cell phenotypes." (PMID 36452504, 2022). "According to RT-qPCR and WB results, the expression of β-catenin and EGFR decreased within LIRI cells and tissues relative to that within control cells and non-carcinoma tissues." (PMID 35972910, 2022). "A431 is previously reported as a carcinoma cell line with an unusually high number of EGFR58, and we thus validated the expression of EGFR in A431 cells by quantitative polymerase chain reaction (qPCR)." (PMID 36376325, 2022). "In all the carcinoma and hematopoietic cancer networks, STAT1 and STAT3 interact with a similar panel of proteins, including MTOR, SRC and EGFR." (PMID 35229974, 2022). "In the study, the EGFR expression in carcinoma cells was prolonged for 10 h when 10 nM of EGF was exerted, as compared to only 4 h of EGFR expression in 0.4 nM EGF." (PMID 36286420, 2022). "Also, Haemophilus parainfluenzae, as a risk factor to survival, may promote the EGFR-WT carcinomas but not EGFR mutant ones, and these cases cannot be treated by targeted TKIs, which is a possible reason for the poor survival." (PMID 35178229, 2022). "Research has shown that RTKs EGFR/MET are responsible for sorafenib resistance and they were highly phosphorylated in multiply carcinoma cells including the lungs, breasts, and pancreas." (PMID 35428350, 2022). "Another example is the epidermal growth factor receptor (EGFR), which is an important receptor tyrosine kinase for signaling in development and metabolism and has become an important target for treating cancers." (PMID 33807006, 2021). "ALK, EGFR, FGFR, FLT3, NTRK, and VEGFR are the most well-known RTKs with aberrant signaling in different cancer types." (PMID 34577598, 2021). "We also noted the possibility of using RNA G-rich oligonucleotides conjugated to a fluorescent probe in a visualization of the density of the endogenous EGFR mRNA in MCF-7, HeLa, and A431 cancer cells." (PMID 34439902, 2021). "Therefore, the EGFR may be another potential anti-cancer target." (PMID 34592904, 2021). "Although EGFR and c-MET seem like promising biomarkers, they are also commonly upregulated in other cancer metastases." (PMID 34298701, 2021). "The EGFR family, crucially involved in the tumorigenesis of multiple cancers, comprises four receptors, namely, EGFR/HER1, HER2, HER3 and HER4." (PMID 33529238, 2021). "Altogether, this study explored the chromatin accessibility landscapes based on ATAC-seq assay and discovered a new eRNA for EGFR gene in ESCC and the reliance of cancer cells on the AP-1 transcription factor." (PMID 34722266, 2021). "Multiple cancer-related PROTACS have been developed so far, and these include PROTACS directed at EGFR, CDK4/6, ERK1/2, and PI3K." (PMID 33809714, 2021). "ERBB2, EGFR and KRAS have FDA-approved drugs for use in cancer therapy, whereas CDKN2A has biological evidence for targetability, but associated drugs are not yet standard-of-care." (PMID 34298611, 2021). "Altogether, silibinin can inhibit cancer hallmarks against NSCLC cells and also inhibited PD-L1 expression through EGFR-mediated PI3K/AKT and JAK2/STAT5 signaling mechanisms." (PMID 34209829, 2021). "Epidermal growth factor receptor (EGFR) is a major receptor tyrosine kinase, frequently overactivated in cancers, with established roles in cell growth and survival." (PMID 33879767, 2021).
cancer (continued). "Pedroza DA demonstrated that PGRMC1 plays a prominent role in regulating the growth of cancer cells by altering the PI3K/AKT/mTOR and EGFR signaling mechanisms in both ER-positive and TNBC cells." (PMID 34746100, 2021). "It is worth highlighting the presence of predictive biomarkers for drugs that are currently in use for treating different cancers, such as PARP, ERBB2, EGFR, PIK3CA, mTOR, and Hedgehog signaling inhibitors." (PMID 34575676, 2021). "HDACs and HSP90 are involved in the activation of several oncogenic pathways in cancer maintenance, including the PI3K/AKT/mTOR, STAT, EGFR, and RAF/MEK/ERK pathways, which were also highly enriched in AML and ALL patient profiles." (PMID 33986242, 2021). "As EGF-EGFR signaling has been implicated as a central channel in the development of multi-aggressive phenotypes by SCP3, we believe that inhibition of EGFR signaling may be an effective strategy to control refractory cancer, especially if there is high SCP3 expression." (PMID 34445562, 2021). "In this cancer type, circRNA CCDC66 induced EGFR overexpression, directly increasing the effects of the MAPK pathway." (PMID 34162394, 2021). "Specifically, the anti-EGFR antibody cetuximab inhibits EGFR and its downstream ERK activation, which hinders cancer cell proliferation, whereas ERK activation is maintained in HER2-amplified cells, even under cetuximab treatment." (PMID 33801379, 2021). "Cancer cell-intrinsic functions of IL6 include promoting proliferation and survival thereby functioning as a bypass pathway in the setting of EGFR-specific TKIs31." (PMID 34001994, 2021). "Brigatinib is a dual kinase inhibitor that targets mutant epidermal growth factor receptor (EGFR) and anaplastic lymphoma kinase (ALK) and is an approved drug for cancer therapy." (PMID 34642691, 2021). "Top classes of mechanism of action amongst targeted cancer compounds included PI3K/AKT/MTOR, EGFR, and HDAC inhibitors." (PMID 34907286, 2021). "In this study, we identified PGRMC1 as a novel binding protein for GL and showed that GL exhibits its mediated anti-cancer effect by inhibiting PGRMC1 function, including EGFR activation and LDL uptake." (PMID 34209885, 2021). "The treatment of EGFR-TKIs induces YAP-mediated anti-apoptosis and dormancy of cancer cells, representing a phenotype of CSCs." (PMID 33562150, 2021). "In cell-based assays, Pz-1 selectively inhibited, in the low nM range, proliferation of cancer cell lines only when positive for RET or TRK-derived oncogenes, with negligible effects in cells carrying different driver oncogenes (RAS, BRAF, EGFR)." (PMID 34373541, 2021). "As TRPV3 is present in the same signaling complex with EGFR and EGFR activity triggers TRPV3, there is a clear functional interplay in between these factors and it potentially plays a role along cancer progression." (PMID 34356643, 2021). "BRAF is a serine-threonine kinase just downstream of EGFR/KRAS that activates the MEK/extracellular signal-regulated kinase (ERK) signalling cascade through its phosphorylation and then promotes cancer cell proliferation." (PMID 34663410, 2021). "Much of the focus in this area has been on EGFR and HER2, which are well-established tumor drivers and targets of effective anti-cancer therapeutics." (PMID 33420373, 2021). "Further, FOS also promotes increased expression of EGFR (HER1/ErbB1) and affects cell differentiation and proliferation during cancer progression." (PMID 34938177, 2021). "Therefore, we speculated that genistein may suppress EGFR in cancer cells." (PMID 34540820, 2021). "Multiple studies have demonstrated that in BRAF V600E mutant cancers, BRAF inhibition can lead to rapid EGFR-mediated feedback activation." (PMID 34071428, 2021).
cancer (continued). "Moreover, cetuximab-AuNPs could be added to the standard chemotherapy and radiotherapy, where the enhanced uptake by specific targeting, and the subsequent improved efficacy of the therapeutic agents/radiation could be a viable approach for the treatment of cancers with EGFR overexpression." (PMID 33499047, 2021). "Among them, the epidermal growth factor receptor (EGFR) is likely the most commonly investigated signaling pathway, renowned for its fundamental role in the tumorigenesis of many cancer types." (PMID 34557197, 2021). "The following figure shows the Alteration frequency type of EGFR, HRAS and MAPK3 in four types of cancer." (PMID 34764329, 2021). "The pyrazoline derivatives consisting of carbothioamide group showed significant EGFR inhibition, showing IC50 values ranging from 1.66 to 1.9 μM, and halted the growth of cancer cells." (PMID 34769090, 2021). "Collectively, our study reveals a critical role of linear ubiquitination in EGFR-mediated NF-κB signaling and that HOIP is a potential drug target for cancer therapy." (PMID 34769306, 2021). "The exosomal miR‐1169 and miR‐260 as potential candidates, which contain specific characteristics that can distinguish between wild‐type EGFR and mutant EGFR NSCLC patients in early‐stage cancers." (PMID 33682961, 2021). "Recently, study discovered that AURKB is responsible for cancer resistance to chemical reagents such as cisplatin and paclitaxel, and it has been established as a potential target to overcome the acquired resistance to EGFR TKIs when patients do not harbor resistance mutations in the EGFR gene." (PMID 33612479, 2021). "Epidermal growth factor receptor (EGFR) belongs to a member of the receptor tyrosine kinase superfamily, which is expressed in various malignant tumors." (PMID 34555268, 2021). "The JNK pathway has been linked to increases in invasiveness, angiogenesis, and metastasis; cancer stem cell (CSC) phenotype; and acquired resistance to EGFR/HER2-targeted therapies." (PMID 34207383, 2021). "EGFR/BRAF, EFRF/KRAS, KRAS/ERBB2 demonstrated a mutually exclusive relationship, consistent with the recent evidence from cancer genomic studies which demonstrated that driver genes are often mutated in a mutually exclusive manner." (PMID 35186718, 2021). "The SRC oncogene was followed by MYC, ERBB/EGFR, and RAS oncogenes whose identification in diverse human cancers consolidated the view of cancer as a genetic disease." (PMID 34070384, 2021). "In terms of mechanism, several studies have found that CVBD, through the CTHRC1-AKT/ERK-Snail pathway or EGFR-FAK-AKT/ERK1/2-Slug pathway, inhibit cancer tumorigenesis through CVBD inducing mitochondrial apoptosis in cancer cells." (PMID 33816313, 2021). "With these advances, novel targeted therapies, including several kinase inhibitors (KI) such as BRAF inhibitors (BRAFi), EGFR inhibitors (EGFRi) and CDK4/6 inhibitors, have been introduced in the clinics for the treatment of a variety of cancer entities." (PMID 34298736, 2021). "The analysis of protein–protein interactions according to the STRING database highlighted EGFR and ESR1 as key nodes and endocrine resistance, Th1 and Th2 cell differentiation and proteoglycans in cancer as key pathways within the network." (PMID 33971902, 2021). "The overexpression of epidermal growth factor receptor (EGFR) in cancer cells leads to abnormal signal transduction and is closely related to the occurrence of cancer." (PMID 33921332, 2021). "Although blocking EGFR palmitoylation hyperactivates EGFR, there are relatively few examples in the literature implicating DHHC enzymes in the initiation or progression of cancer." (PMID 34610265, 2021). "Molecularly targeted therapy including small molecular drugs or monoclonal antibodies targeting EGFR, VEGF, and HER2 has been developed due to the limitations of traditional cancer treatment." (PMID 34221006, 2021).
cancer (continued). "The alteration of signaling involved in cancer microenvironment, including VEGF, FGFR, EGFR, GPCR, NTRKs and TGFB, etc. have also been found in CSCs." (PMID 34134623, 2021). "In line with this, the cBioPortal database OncoPrint analysis shows that most of these RTKs have the highest alteration rate, such as EGFR = 10%, ERBB2 = 7%, BRAF = 7%, ROS1 = 5%, and MET = 3%, in 165 (44,752 patients/46,632 samples) cancer cohort studies." (PMID 34769090, 2021). "Emerging evidence has proposed that EGFR TKI resistance operates through an integrin-mediated pathway, with some showing the increased involvement of FAK in the resistance of cancer cells to EGFR TKIs." (PMID 34375550, 2021). "We showed here that maspin subcellular localization is controlled by EGFR, JAK-STAT3 and PI3K-Akt pathways, which are often dysregulated in tumorigenesis and cancer progression." (PMID 34391444, 2021). "Another important glucose transporter participating in EMT and cancer progression is GLUT-3, whose expression is upregulated by Zeb1, TCF4/β-catenin, HMGA1, and EGFR." (PMID 33673109, 2021). "As a ligand for EGFR, DCN prolongs p21 production and promotes caveolar-mediated endocytosis of EGFR for reduced proliferation of cancer cells." (PMID 34638928, 2021). "For the EGFR wild‐type samples, the top six pathways selected for analysis include ECM‐receptor interaction, cancer miRNA in cancer, focal adhesion, PI3 K‐Akt signaling pathway, MAPK signaling pathway, and Ras signaling pathway." (PMID 33682961, 2021). "Another group of biomarkers targeted for cancer therapy is RTKs: IGFR, EGFR VEGFR, c-Met, and its ligands." (PMID 34439182, 2021). "Gene set enrichment-based pathway analysis indicated the activation of several cancer-promoting and cell migration/invasion-related signaling pathways, including RAS, EGFR, focal adhesion, VEGFR and cytoskeletal rearrangement pathways." (PMID 34439388, 2021). "In agreement with this, GL, at approximately 50 μM, suppressed PGRMC1-mediated EGFR activation and LDL uptake, enhancing anti-cancer activity." (PMID 34209885, 2021). "Although we are currently continuing to evaluate the clinical significance of L858R ctDNA kinetics measured by NOIR-SS during EGFR-TKI treatment, further studies are warranted to establish the usefulness of NOIR-SS for managing patients with cancer." (PMID 34294857, 2021). "TMEM52B suppression enhanced EGFR activation and the downstream MAPK and AKT signaling pathways, leading to cancer cell invasion and survival." (PMID 33641663, 2021). "In ovarian cancer, cancer cell proliferation was induced by SPINK1 and was further abolished by EGFR inhibitor." (PMID 33916984, 2021). "Overall, our study reveals a novel linear ubiquitination signaling axis of EGFR and that perturbation of HOIP E3 ubiquitin ligase activity is potential targeted cancer therapy." (PMID 34769306, 2021). "In colorectal cancer, the treatment of tumours with an EGFR inhibitor led to an increased secretion of EGF by stromal fibroblasts and conferred resistant of neighbouring cancer cells to the treatment via activation of MAPK signalling." (PMID 34298736, 2021). "As HAFG binds specifically to EGFR, Cy5.5-labeled HAFG would be used to diagnose EGFR-overexpressing cancers by monitoring the fluorescence." (PMID 34502049, 2021). "To evaluate the sensitivity of HNSCC cell lines, first we investigated the in vitro effects of EGFR, RAS and c-MET inhibitors on cancer cell proliferation." (PMID 34257586, 2021). "Berberine modulates various signaling pathways, including PI3K/Akt, MAPKs, AMPK, STAT3, NF-κB, EGFR, ROS, and HIF-1α, to sensitize cancer cells to a broad spectrum of cancer therapies." (PMID 34576028, 2021). "As a member of the epidermal growth factor receptor (EGFR) family, tyrosine kinase receptor 2 (ERBB2) is important to the research of cancer biology and cardiac function and development." (PMID 35071383, 2021).